COASY (Coenzyme A synthase)
Description:
Bifunctional enzyme that catalyzes the fourth step of the coenzyme A biosynthetic pathway, the adenylation of 4'-phosphopantetheine, and the fifth step, the phosphorylation of dephospho-CoA to CoA.
Synonyms: PPAT; DPCK; NBP; NBIA6; PCH12; UKR1; pOV-2
Tractability: PROTAC: ubiquitination databases record sites on it; its protein half-life has been measured.
Target class: Enzyme; Transferase
Gene: Protein-coding gene on chromosome 17 (42,561,467 to 42,566,277, forward strand). Ensembl gene ENSG00000068120.
Subcellular location: Cytoplasm, cytosol; Mitochondrion matrix
Subcellular location (Human Protein Atlas): Mitochondria; Connecting piece
Pathways (Reactome):
Metabolism: Coenzyme A biosynthesis
Gene Ontology:
Molecular function: dephospho-CoA kinase activity; pantetheine-phosphate adenylyltransferase activity; protein binding; ATP binding; catalytic activity
Biological process: coenzyme A biosynthetic process
Cellular component: cytosol; extracellular exosome; mitochondrial matrix; mitochondrion; mitochondrial outer membrane
Genetic constraint (gnomAD): Loss-of-function variants: 32 observed, 54.34 expected, observed/expected ratio (o/e) 0.59, 90% interval 0.44 to 0.79. The upper end of that interval is the gene's LOEUF score, 0.79, which puts it in group 3 of 6, group 1 being the genes least tolerant of losing a copy. Missense variants: 730 observed, 750.3 expected, observed/expected ratio (o/e) 0.97, 90% interval 0.92 to 1.03. Synonymous variants: 285 observed, 312.08 expected, observed/expected ratio (o/e) 0.91, 90% interval 0.83 to 1.01.
Homologues: Orthologues: chimpanzee COASY (99% identical), macaque COASY (98% identical), dog COASY (91% identical), rabbit COASY (91% identical), pig COASY (88% identical), mouse Coasy (87% identical), rat Coasy (86% identical), guinea pig COASY (82% identical), tropical clawed frog coasy (59% identical), zebrafish coasy (51% identical), Drosophila melanogaster Ppat-Dpck (34% identical), Caenorhabditis elegans Y65B4A.8 (32% identical). Paralogues in human: DCAKD (11% identical).
Diseases named in the same sentence as COASY in open-access papers:
COASY is named in the same sentence as 37 diseases in open-access papers, as found by Europe PMC text mining. Sharing a sentence is not in itself a finding about the gene and the disease. The quoted sentences say what the papers report.
Neurodegeneration (7 papers, 2020 to 2025). Progressive loss of neural cells and tissue. "Variants in PANK2 cause pantothenate kinase-associated neurodegeneration (PKAN) (OMIM: #234200), while mutations in COASY cause COASY Protein-Associated Neurodegeneration (CoPAN) (OMIM: #615643)." (PMID 39301217, 2024). "Mutations in PPCS and PPCDC are associated with forms of dilated cardiomyopathy, while variants in PANK2 and COASY cause neurological disorders classified as Neurodegenerations with Brain Iron Accumulation (NBIA)." (PMID 39301217, 2024). "The view that the defect in CoA biosynthesis is at the center of the molecular mechanism of PKAN is supported by the discovery that mutations in CoA synthase, COASY, cause a similar neurodegenerative disease, CoPAN (COASY Protein-Associated Neurodegeneration)." (PMID 33396642, 2020). "Mutations in CoA synthesis enzymes PANK2 and COASY cause the neurodegenerative diseases pantothenate kinase associated neurodegeneration (PKAN; MIM #234200) and COASY protein associated neurodegeneration (CoPAN; MIM #615643) respectively." (PMID 41279021, 2025). "Recently, a hot spot mutation in the COASY gene was observed in a subset of neurodegeneration patients with brain iron accumulation (NBIA) and a distinct set of symptoms, accordingly named COASY protein-associated neurodegeneration (CoPAN)." (PMID 32676515, 2020).
arthrogryposis (4 papers, 2020 to 2024). A rare, non-progressive congenital disorder characterized by multiple joint contractures which are present at birth. "In addition, a single report described four patients with biallelic LoF COASY variants affecting the C-terminus of the protein and prenatal onset of pontocerebellar hypoplasia, microcephaly and arthrogryposis." (PMID 35180557, 2022). "More recently, loss-of-function variants of COASY associated with complete loss of the enzyme were reported in two cases of severe pontocerebellar hypoplasia, prenatal onset microcephaly, and arthrogryposis, with an invariable lethal phenotype in the perinatal period." (PMID 33352696, 2020). "More recently, mutations in COASY associated with the complete absence of the protein were reported in two cases of pontocerebellar hypoplasia, microcephaly, and arthrogryposis with an invariable perinatal lethal phenotype." (PMID 33352696, 2020).
microcephaly (4 papers, 2020 to 2024). A congenital or acquired developmental disorder in which the circumference of the head is smaller than normal for the person's age and sex. "Thirteen fetuses/newborns with complete loss-of-function COASY variants exhibited pontocerebellar hypoplasia type 12 (PCH12), a fatal inherited neurodevelopmental disorder characterized by microcephaly and perinatal death, without brain iron accumulation." (PMID 39301217, 2024).
neurodegeneration with brain iron accumulation (4 papers, 2016 to 2024). "Germline mutations of COASY have been previously linked to an autosomal recessive disorder (neurodegeneration with brain iron accumulation, NBIA) and pontocerebellar hypoplasia." (PMID 36857430, 2023). "Germline mutations of COASY have been reported in an autosomal recessive neurodegenerative disorder called neurodegeneration with brain iron accumulation (NBIA)." (PMID 36857430, 2023). "Loss of function mutations in either PANK or COASY gives rise to disorders which fall into a group categorized broadly as neurodegeneration with brain iron accumulation (NBIA)." (PMID 36475414, 2022). "Regarding mutations in the COASY gene, one is known to be associated with neurodegeneration with brain iron accumulation (NBIA)." (PMID 27992572, 2016).
breast carcinoma (3 papers, 2012 to 2020). "Next, we examined whether COASY expression in primary tumors was associated with different clinical outcome in breast cancer cohorts using prognostic database PROGgene V235." (PMID 29531224, 2018). "Furthermore, knocking down COASY by siRNA sensitized HER2+ (ER±/PR±/HER+) breast cancer cells to trastuzumab treatment; however, this effect needs to be verified in in vivo models." (PMID 33260564, 2020). "Moreover, pantothenate kinase 3 (PANK3) and Coenzyme A synthase (COASY) are known breast cancer genes." (PMID 23281707, 2012). "We found that COASY knockdown similarly triggered multinucleation in multiple cancer cell lines, including A549 (lung adenocarcinoma), MDA-MB-231 (breast cancer), PANC-1 (pancreatic cancer), and non-cancerous cell line ARPE-19 (human retina)." (PMID 29531224, 2018). "The expression pattern of COASY in breast cancer cells was not compared to that in normal cells; however, some studies have reported that knocking out COASY in triple-negative breast cancer (ER-/PR-/HER2-) resulted in reduced cell proliferation and migration." (PMID 33260564, 2020).
pantothenate kinase-associated neurodegeneration (3 papers, 2020 to 2025). "CoA deficiency is associated with severe human diseases, such as Pantothenate Kinase-Associated Neurodegeneration (PKAN) and CoASY protein-associated neurodegeneration (CoPAN), which are linked to genetic mutations in Pantothenate Kinase 2 (PANK2) and CoA Synthase (CoASY)." (PMID 39985665, 2025).
pontocerebellar hypoplasia type 12 (3 papers, 2023 to 2024). "Thereafter, COASY-recessive loss-of-function variants have been found in thirteen fetuses/neonates from seven unrelated families with pontocerebellar hypoplasia type 12 (PCH 12)." (PMID 36983025, 2023). "Recessive variants of this gene cause an exceptionally rare and devastating disease called COASY protein-associated neurodegeneration (CoPAN) while complete loss-of-function variants in COASY have been identified in fetuses/neonates with Pontocerebellar Hypoplasia type 12 (PCH 12)." (PMID 39301217, 2024).
dilated cardiomyopathy (2 papers, 2021 to 2023). Cardiomyopathy which is characterized by dilation and contractile dysfunction of the left and right ventricles. "Defects in the CoA biosynthesis pathway in humans caused by mutations in PanK, PPCS, or CoA synthase (CoASY, a bifunctional PPAT/DPCK enzyme) lead to a variety of diseases including neurodegeneration and dilated cardiomyopathy." (PMID 34969059, 2021).
Kufor-Rakeb syndrome (2 papers, 2020 to 2021). Kufor-Rakeb syndrome (KRS) is a rare genetic neurodegenerative disorder characterized by juvenile Parkinsonism, pyramidal degeneration (dystonia), supranuclear palsy, and cognitive impairment. "Finally, two probands and five probands, respectively, are described for Kufor–Rakeb syndrome (ATP13A2 gene) and CoPAN (COASY protein-associated neurodegeneration; COASY gene)." (PMID 33092153, 2020).
lung adenocarcinoma (2 papers, 2018 to 2025). A carcinoma that arises from the lung and is characterized by the presence of malignant glandular epithelial cells. "This study investigates the significance and potential mechanisms of novel mitochondrial autophagy-related biomarkers COASY, FTSJ1, and MOGS in lung adenocarcinoma (LUAD)." (PMID 40313958, 2025).
pontocerebellar hypoplasia (2 papers, 2020 to 2024). Pontocerebellar hypoplasias (PCH) are a rare heterogeneous group of diseases characterized by hypoplasia and atrophy and/or early neurodegeneration of the cerebellum and pons. "Variants of the COASY gene with near complete loss of function cause a subtype of pontocerebellar hypoplasia (PCH)." (PMID 33260564, 2020).
rectal cancer (2 papers, 2020 to 2022). A primary or metastatic malignant neoplasm that affects the rectum. "To evaluate patient heterogeneity, we analyzed COASY expression in pretreatment human rectal cancers and found levels varied among patients, and that increased levels were directly related to radiation resistance." (PMID 32676515, 2020). "Our findings may have broader implications beyond rectal cancer as the level of COASY was found to be significantly overexpressed in tumors compared to normal tissues in several other cancers." (PMID 32676515, 2020).
triple-negative breast carcinoma (2 papers, 2018 to 2020). An invasive breast carcinoma which is negative for expression of estrogen receptor (ER), progesterone receptor (PR), and human epidermal growth factor receptor 2 (HER2). "In a genetic screen, we serendipitously identified that COASY knockdown reduced the viability of a triple-negative breast cancer cell line (MDA-MB-231)." (PMID 29531224, 2018).
anemia (1 paper, 2018). A reduction in the number of red blood cells, the amount of hemoglobin, and/or the volume of packed red blood cells. "As expected, anemia rats showed obvious inhibition of ACSS1 and COASY." (PMID 29551975, 2018).
COASY protein-associated neurodegeneration (1 paper, 2024). "This protein is encoded by the CoA synthase (COASY) gene, whose mutations result in the NBIA subtype called COASY Protein-Associated Neurodegeneration (CoPAN), a rare autosomal recessive disease occurring in less than one in every million people." (PMID 39195264, 2024).
colorectal cancer (1 paper, 2022). A primary or metastatic malignant neoplasm that affects the colon or rectum. "COASY knockdown reduced activity of the PI3K pathway and DNA repair, which sensitised colorectal cancer to radiotherapy in vivo and in vitro, and thus, may also be a therapeutic target alongside radiotherapy and chemotherapy in CRPC." (PMID 35326402, 2022). "Although COASY inhibition did not alter proliferation in triple-negative breast cancer and colorectal cancer cell lines, the outcome in PCa may be different for several reasons." (PMID 35326402, 2022).
Down syndrome (1 paper, 2016). "In AD research, it has been reported that COASY single nucleotide polymorphisms (SNPs) are a risk for developing AD in Down Syndrome patients and it has been observed that cholinergic dysfunction in AD is due to reduced production of acetyl CoA." (PMID 27992572, 2016).
epilepsy (1 paper, 2024). A brain disorder characterized by episodes of abnormally increased neuronal discharge resulting in transient episodes of sensory or motor neurological dysfunction, or psychic dysfunction. "Our data suggest that epilepsy may be a common clinical feature of COASY‐associated diseases." (PMID 38750253, 2024).
lipid storage myopathy (1 paper, 2024). "Given the crucial role of the COASY enzyme and the complexity behind the regulation of its expression and, consequently CoA levels, it is not surprising that COASY variants are also responsible for other clinical phenotypes such as riboflavin-responsive lipid storage myopathy." (PMID 39301217, 2024).
Obesity (1 paper, 2024). Accumulation of substantial excess body fat. "Consequently, epigenetic changes in the mitochondria-related gene COASY in MSCs imposed by obesity could alter their capacity to induce effective repair in individuals with neurodegenerative disorders." (PMID 38824145, 2024).
Parkinsonism (1 paper, 2017). Characteristic neurologic anomaly resulting from degeneration of dopamine-generating cells in the substantia nigra, a region of the midbrain, characterized clinically by shaking, rigidity, slowness of movement and difficulty with walking and gait. "It is also reasonable that dysfunction of DJ-1 causes Parkinsonism as dysfunction of genes involved in the CoA biosynthetic pathway (PANK2 and COASY) trigger neurodegeneration with Parkinsonism." (PMID 28993701, 2017).
Spastic paraplegia (1 paper, 2023). Complete loss of the ability to move the lower limbs accompanied by spasticity of the lower limbs. "The same occurred with a PCYT2 mutation in patient IDSPG27, ranked 3 in a VCF file with 1738 variants, because PCYT2 protein interacts with other proteins associated with spastic paraplegia such as PNPLA6 or COASY." (PMID 37679823, 2023).
cancer (5 papers, 2018 to 2025). A tumor composed of atypical neoplastic, often pleomorphic cells that invade other tissues. "Therefore, cancer cells may employ different strategies to overcome CoASY deficiency." (PMID 39985665, 2025). "Together, these data suggest the strong correlation of reduced COASY expression level with taxol resistance and poor clinical outcome of cancer patients." (PMID 29531224, 2018).
tumor (2 papers, 2023 to 2025). "Based on research into COASY, FTSJ1, and MOGS, this study investigates their associations with immune cell infiltration and the tumor microenvironment, aiming to identify novel targets and strategies for personalized LUAD treatment." (PMID 40313958, 2025). "Likewise, we observed splicing variation in the KY011 tumor for COASY." (PMID 38069324, 2023).
COASY also shares sentences with these, for which no sentence is quoted: malaria (2 papers); neurodevelopmental disorder (2); protein (2); aceruloplasminemia (1); axonal neuropathy (1); Cerebellar atrophy (1); Cognitive impairment (1); diabetes (1); Dystonia (1); fatty acid hydroxylase-associated neurodegeneration (1); neuroferritinopathy (1); neurological disease (1); pancreatic cancer (1).